RNU6-748P (RNA, U6 small nuclear 748, pseudogene)
Gene: Small nuclear RNA gene on chromosome 8 (98,462,944 to 98,463,050, reverse strand). Ensembl gene ENSG00000207378.
Homologues: Orthologues: chimpanzee U6 (100% identical), macaque U6 (94% identical). Paralogues in human: RNU6-1060P (94% identical), RNU6-41P (93% identical), RNU6-116P (93% identical), RNU6-15P (93% identical), RNU6-19P (93% identical), RNU6-12P (92% identical), RNU6-13P (92% identical), RNU6-166P (92% identical), RNU6-25P (92% identical), RNU6-31P (92% identical), RNU6-32P (92% identical), RNU6-33P (92% identical), and 1289 more.